BRAF (B-Raf proto-oncogene, serine/threonine kinase)
Diseases named in the same sentence as BRAF in open-access papers (continued):
Sharing a sentence is not in itself a finding about the gene and the disease.
melanoma (continued). "Of interest, our preliminary data also suggest that the site of mutation may be important, since the subgroup with V600K BRAF mutation (as opposed to V600E) was associated with more brain metastases, and shorter time for both disease-free and overall survival from diagnosis in melanoma." (PMID 22039425, 2011). "In melanoma, patients with germline variations in MC1R have a higher frequency of somatic BRAF mutations in their melanomas than patients without MC1R variants." (PMID 20885788, 2010). "Since BRAF is not active in RAS mutant melanoma cells, we measured T529NBRAF activity using transient expression in COS cells." (PMID 20141835, 2010). "In BRAFWT melanoma cells, BRAF was either not detectable or was about 10- to 50-fold less active than its mutant counterpart." (PMID 20149136, 2010). "This study makes the unexpected observation that combined BRAF and MEK inhibitor treatment enhances the levels of apoptosis before resistance to BRAF inhibition is even acquired, suggesting that the recovery of melanoma signalling occurs much earlier than previously suspected." (PMID 20531415, 2010). "The prevalence of BRAFV600E mutations in melanocytic nevi suggests that BRAF mutations may be important initiating events, but do not inexorably lead to melanoma, as the estimated lifetime risk of progression of a particular nevus to melanoma is roughly 1 in 7,000." (PMID 24212610, 2010). "SRB assay of growth inhibition following treatment with 17-AAG indicated that the drug reduced cell proliferation in the two human melanoma cell lines studied, with GI50 values of 21±5 nM for the BRAF mutant SKMEL28 cells and 13±2 nM for the BRAF WT CHL-1 cells." (PMID 21037799, 2010). "Nevertheless, the mechanisms by which BRAF signalling promotes melanoma development and/or progression to metastatic disease are not well defined and effective melanoma therapy remains elusive." (PMID 19724275, 2009). "It is interesting to note that several studies also suggest the relevance of combined inhibition of CRAF and BRAF in a BRAF mutant context for efficacy and may prove to be relevant strategy for treatment of both NRAS and BRAF mutant melanomas." (PMID 19492075, 2009). "Analysis of BRAF and NRAS mutations in our human melanoma cell lines shows that WM3211 cells do not have the common activating mutations in these genes, yet these cells express increased amounts of HIF-1α protein and mRNA under normoxic conditions." (PMID 19919690, 2009). "We report a 60-year-old male with a history of BRAF-negative malignant melanoma and a new melanoma in situ, who presented with diabetes insipidus, hypogonadism, ataxia, blurred vision, dysarthria, headache, personality changes, and disturbed sleep patterns with kicking and mumbling." (PMID 42117125, 2026). "We found that mutant BRAF is overexpressed in melanoma but not thyroid cancer." (PMID 40869231, 2025). "BRAF inhibitors (BRAFi), whether used as monotherapy or in combination with MEK inhibitors (MEKi), have demonstrated remarkable clinical efficacy in a substantial proportion of cancer patients, particularly those with melanoma harboring mutant BRAFV600E." (PMID 40681872, 2025). "The literature suggests that malignant NCH may be distinct from melanoma based on the lack of GNAQ, NRAS, BRAF, and KIT mutations that are commonly identified in melanoma." (PMID 40265343, 2025). "Furthermore, mucosal melanomas exhibit higher frequencies of KIT mutations rather than BRAF mutations, making standard BRAF-targeted therapies less effective in these cases." (PMID 40395262, 2025). "Selective BRAF inhibitors (dabrafenib, vemurafenib, encorafenib) and MEK inhibitors (trametinib, cobimetinib, binimetinib) have demonstrated robust clinical activity, particularly in melanoma, non-small cell lung carcinoma (NSCLC), and colorectal carcinoma harboring MAPK pathway alterations." (PMID 41228293, 2025).
melanoma (continued). "As characteristics and survival by genotype were explored in the BRAF-tested cohort, this cohort may not be generalizable to the population of patients with melanoma who did not undergo testing." (PMID 40902091, 2025). "Our findings suggest that, conversely to non-mutated melanomas, BRAF, NRAS, and cell cycle gene-mutated melanomas were significantly associated with clinical, histopathological, and dermoscopic characteristics underlying a more aggressive melanoma phenotype." (PMID 40867317, 2025). "It is also important to note that the effects of ALDH2 downregulation on tumor growth and drug response may be cell line-dependent and may not extend to BRAF-WT melanoma." (PMID 40558540, 2025). "The phase II CHRONOS trial in metastatic colorectal cancer provided proof of principle that cfDNA could guide therapeutic rechallenge with panitumumab, and the DYNAMIC trial will use ctDNA to direct AT with BRAF and MEK inhibitors in advanced malignant melanoma." (PMID 40299825, 2025). "However, there is also evidence that SIRT5 is not required for BRAFV600E melanoma growth in vivo and did not sensitize BRAF-mutant melanoma to BRAF inhibitor therapy." (PMID 39935431, 2025). "Notably, buparlisib combined with a BRAF inhibitor (NCT01512251) did not yield a well-tolerated response in BRAF V600 melanoma patients." (PMID 40399946, 2025). "NGS offers a broader scope compared single-gene techniques; however, for monitoring BRAF V600-mutant melanoma patients treated with BRAF/MEKi, its use may not be necessary." (PMID 39859576, 2025). "Besides targeted therapy, immunotherapy is a parallel treatment approach for melanoma patients, regardless of BRAF status, by triggering the cytotoxic potential of the powerful immune system to eliminate tumor cells." (PMID 40617808, 2025). "Based on the results of the global, phase III COLUMBUS trial, the BRAF/MEK inhibitor combination, encorafenib plus binimetinib, was approved in Japan in early 2019 for the treatment of BRAF-mutant, at the V600 locus (BRAF V600), unresectable malignant melanoma." (PMID 39918770, 2025). "This rarity of this mutation in SS posed two challenging questions for the personalized medicine: whether BRAF inhibitors (including vemurafenib [Vem] and dabrafenib), known for efficacy in BRAFV600E melanoma, could be applied to treat SS and which inhibitor should be chosen." (PMID 40054460, 2025). "The absence of established molecular drivers associated with melanoma such as BRAF V600E mutations, along with the lack of PRAME staining expression by immunohistochemistry, a marker that is often positive in melanoma, can help confirm a benign diagnosis in NCH." (PMID 40265343, 2025). "Our results show that Wnt/β-catenin signaling plays a major role in controlling metabolic plasticity and drug resistance, and that targeting this signaling could produce strong interference with these activities in BRAF inhibitor- and MEK inhibitor-resistant melanomas." (PMID 40558548, 2025). "Combined inhibition of BRAF (by vemurafenib) and HDAC (by 4-phenylbutyrate) upregulated MC1R expression in BRAF-mutant melanoma cells leading to an increased response of BRAFV600E A2058 melanoma-bearing mice to the MC1R-targeting radiolabeled peptide [212Pb]DOTA-MC1L." (PMID 39935431, 2025). "However, oncogenic activation of BRAF in melanocytes, the benign counterpart of melanoma cells, does not convert melanocytes into malignant melanoma." (PMID 41258756, 2025). "Unlike KRAS and BRAF mutations, NRAS mutations may be more significant in melanoma than CRC, but can still be seen in both cancers." (PMID 40447784, 2025). "Furthermore, for patients with BRAF wild-type melanoma who have developed resistance to anti-PD-1 therapy, no standard treatment options currently exist." (PMID 40647561, 2025).
melanoma (continued). "Preclinical in vivo data show that BRAF inhibitors do not impair lymphocyte viability, proliferation, or cytokine production at therapeutic concentrations, nor do they negatively impact serum cytokine levels or leukocyte counts in melanoma patients." (PMID 40332392, 2025). "As with blue nevi, melanoma arising in blue nevi is also positive for melanocytic markers and lacks expression of BRAF V600E protein on immunohistochemistry, which, as already stated, is not the most reliable marker, as many melanomas, as well as other spindle cell cutaneous neoplasms, also lack it." (PMID 40843873, 2025). "Furthermore, the results of combined immune checkpoint and kinase inhibitor therapy was recently summarized, and a triple therapy consisting of atezolizumab, the BRAF inhibitor vemurafenib and the MEK inhibitor cobimetinib was approved as first‐line treatment in BRAFV600 melanoma patients." (PMID 39995112, 2025). "The biopsy results of the left groin lymph node proved a BRAF-negative melanoma recurrence." (PMID 40012549, 2025). "Thus, BRAF inhibition in melanoma represents effective targeted therapy but not stable reversion in most cases." (PMID 41614813, 2025). "However, MMRi62 activity in solid tumor cells such as melanoma cells, especially in BRAF inhibitor resistant melanoma cells, have not been explored." (PMID 40649216, 2025). "A BRAF inhibitor, encorafenib, combined with a MEK inhibitor, binimetinib, was approved in Japan in early 2019 for the treatment of BRAF V600-mutant, unresectable malignant melanoma based on results of the global phase III trial, COLUMBUS, conducted in various countries including Japan." (PMID 39918770, 2025). "However, BRAF mutations alone are not sufficient for BMs to occur, and there is proof that PTEN gene silencing cooperates with BRAFV600E mutations in melanoma progression via the phosphoinositide 3-kinase (PI3K)/AKT pathway activation." (PMID 40076927, 2025). "Combined MAPK targeting via cobimetinib (MEK1/2 inhibitor) and dabrafenib (BRAF inhibitor), a clinical approach used to abrogate rapid acquired resistance to MAPK targeting resulted in deeper and more prolonged responses than monotherapy AZD6244 in BRAF PTEN melanoma." (PMID 39636745, 2025). "Despite the success of anti-BRAF therapy in melanoma, data from randomized clinical trials are lacking for targeted therapy against BRAF mutations—typically the V600E variant—in pancreatic adenocarcinoma, which is associated with a poor prognosis under traditional cytotoxic chemotherapy." (PMID 41367868, 2025). "No clinical trials have yet reported the efficacy of tazemetostat in patients with melanoma, but preclinical studies have suggested EZH2-targeted therapies may interfere with melanoma progression and metastasis and could be a target for combinations with either ICI or BRAF-targeted therapy." (PMID 39984702, 2025). "Moreover, there are differences in prognosis between BRAF-mutant and BRAFWT melanomas." (PMID 41010758, 2025). "Importantly, although Rac1-driven melanoma cells display reduced dependence on BRAF/MEK, they are not completely ERK-independent." (PMID 41109929, 2025). "Moreover, there is currently no established treatment for BRAF wild-type melanoma that is resistant to anti-PD-1 antibodies." (PMID 40647561, 2025). "Given that guidance does not routinely recommend BRAF-testing stage I melanoma, this could be explained by BRAF testing on recurrence and targeted testing." (PMID 40902091, 2025). "The Managed Access Program (MAP) was run in Italy from June 2018 to December 2019 to provide D + T in adjuvant settings to patients with BRAF V600 stage III melanoma following complete tumor resection and without alternative treatment options; roughly 550 patients were involved." (PMID 39682258, 2024).
melanoma (continued). "As the efficacy of BRAF inhibitor plus MEK inhibitor (BRAFi/MEKi) is limited in patients with elevated LDH levels, nivo/ipi combination therapy could be a first-line immunotherapy for BRAF-mutant advanced melanoma with a high tumor burden." (PMID 39337055, 2024). "BRAF/MEK inhibition has pleiotropic immunomodulatory effects like increased CD8+ T cell counts, increased major histocompatibility complex class I, and increased tumor antigen expression in melanoma and a concomitant reduction of the immunosuppressive tumor micromilieu." (PMID 39165562, 2024). "Switching to a 3D culture system with melanoma cell lines capable of forming spheroids, both the 451LU and MDA-MB-435 melanoma cell lines displayed dampened and even reduced tumor spheroid sizes (area μm2) upon treatment with dual BRAF/MEK inhibitors for a total of 72 h." (PMID 38730718, 2024). "An important feature of our case was the BRAF-negative status of the melanoma." (PMID 39119371, 2024). "Immune checkpoint inhibitors (ICIs) and the target therapy with BRAF and MEK inhibitors significantly changed the outcome of patients with metastatic melanoma and several studies have also shown their benefit in the adjuvant setting for the delay of recurrence in stage III melanoma patients." (PMID 39148899, 2024). "Moreover, while we imply the superiority of immunotherapy over chemotherapy in melanoma treatment, it is important to recognize that the chemotherapy group consists of BRAF/MEK inhibitors, which may be the first‐line treatment in select melanoma cases." (PMID 38186321, 2024). "However, our proposal of alternate signaling pathways becoming activated is in agreement with more recent studies showing that MAPK-reactivation does not occur in BRAF(V600E) melanoma cells that cycle slowly in vemurafenib." (PMID 38473364, 2024). "CD64-expressing cDC2 are not restricted to the BRAF-mutant D4M tumor model as this DC subtype could also be detected in the melanoma mouse model B16-ovalbumin (OVA) in the tumor tissue but also tumor-draining LN." (PMID 38631706, 2024). "Finally, the ongoing exploration of combination therapies, such as BRAF/MEK inhibitors paired with novel immune modulators or metabolic reprogramming agents, is crucial for determining their efficacy and safety in patients with BRAF-mutant melanoma." (PMID 39336897, 2024). "Prospective studies with ICB and BRAF/MEKi show comparable response rates in patients with asymptomatic melanoma brain metastasis as compared to patients without CNS involvement; however, once patients become symptomatic or require steroids, ICB becomes less performant." (PMID 39682270, 2024). "Instead, ipilimumab treatment could be of great value in patients with BRAF/NRAS-wildtype melanoma and without brain metastases, with several benefits to long-term survival, although a larger dataset is needed for a more precise indication." (PMID 39410017, 2024). "In addition, PD1 blockade dominated the adjuvant melanoma landscape with only 22 patients having received BRAF/MEKi, meaning that our adjuvant cohorts are not fully balanced, reflecting current preferences in medical care." (PMID 38473216, 2024). "In addition, no targeted therapy has been approved for BRAF-WT melanomas, despite the fact that this subgroup accounts for the majority of cases, often has activation of the MAPK pathway, and has an aggressive cell biology with an unfavorable prognosis." (PMID 38263136, 2024). "Although complete inhibition of the MAPK pathway was already achieved at nanomolar concentrations of trametinib, there was almost no induction of apoptosis in BRAF-WT melanoma cells within three days of treatment with MEKi, as indicated by the absence of sub-G1 cells in the cell cycle analysis." (PMID 38263136, 2024). "Moreover, many researchers suggest that targeting the RB pathway in synergistic therapies may overcome resistance to BRAF and MEK inhibitors in melanoma." (PMID 39598629, 2024).
melanoma (continued). "Furthermore, the ESMO guidelines for the characterization of the diagnosis and treatment of melanomas suggest not to be limited to the single analysis of the BRAF V600 locus." (PMID 38667446, 2024). "However, features relating SVs across histologic subtypes, or genomic (BRAF-, (N)RAS-, and NF1-mutant and triple-wild-type [TWT]) subtypes of melanoma (which have been shown to have distinct secondary driver genes and pathways), remain incompletely characterized." (PMID 38758740, 2024). "However, although the response rate was 40% in treatment-naïve patients with known BRAF mutations, it was only 10% for the cases with BRAF-WT melanoma and none of seven patients with NRAS-mutated melanoma showed a response." (PMID 38263136, 2024). "Based on our findings, the effectiveness of triple therapy as a first-line intervention in BRAF-mutant melanoma is not well supported; additional studies are required to identify the potential population who could still benefit from triple therapy." (PMID 39684531, 2024). "Finally, we found that VARS does not impact BRAF expression nor MAPK pathway activation in the tested BRAFV600E melanoma SENS or RES cultures." (PMID 38849541, 2024). "Similarly, profiling of 46 melanoma samples including melanoma samples, patient-derived cultures and cell lines revealed that a differential putative bivalent chromatin state separated the NRAS and BRAF mutant melanoma subtypes." (PMID 38385532, 2024). "Therefore, alantolactone combined MAPKi could dual suppress STAT3 and BRAF/MEK/ERK1/2 pathways, consequently inhibiting the expression of downstream Klf4, Oct4, Sox2 and c-Myc proteins, to enhance sensitivity of resistant melanoma to MAPKi." (PMID 38822350, 2024). "Furthermore, given the inhibitory characteristics of ABT-751, particular value could be found in combination with P-gp substrate BRAF and MEK inhibitors approved for melanoma." (PMID 38226983, 2024). "However, while the high frequency of BRAF mutations (20–30%) and excellent objective response rate (ORR 60–70%) indicate the clinical value of BRAF-targeted therapy, the remaining 80% of melanoma patients do not benefit from targeted therapy." (PMID 39025927, 2024). "Systemic therapies indicated for patients with completely resected stage III or IV melanoma in the adjuvant setting include the immuno-oncology (I-O) agents nivolumab and pembrolizumab, as well as the BRAF plus MEK inhibitor combination of dabrafenib plus trametinib (for BRAF-mutant disease)." (PMID 38713408, 2024). "Additionally, it can be utilized for various preclinical studies focusing on non-immune-based therapies and BRAF-targeted therapies, which are commonly applied to melanoma patients." (PMID 38570556, 2024). "Meningeal melanocytomas and melanomas do not usually harbor HRAS, KRAS, BRAF, or KIT mutations." (PMID 39061148, 2024). "Recent studies suggest a connection between BRAF activity and nuclear pore complexes (NPCs), indicating that alterations in NPC function may contribute to dysregulated nuclear-cytoplasmic transport in BRAF-mutant melanomas, further promoting tumor progression." (PMID 39459201, 2024). "However, in contrast to metastatic patients with BRAF wild-type melanoma, serum S100B was not a prognostic factor for OS in metastatic patients with BRAF mutant melanoma." (PMID 39272837, 2024). "No prospective data were available prior to 2021 to inform selection between combination BRAF and MEK inhibition versus dual blockade of programmed cell death protein-1 (PD-1) and cytotoxic T lymphocyte antigen-4 (CTLA-4) as first-line treatment options for BRAFV600-mutant melanoma." (PMID 38167503, 2024). "To date, precision therapies targeting the BRAF/MEK/ERK pathway, including BRAF inhibitor (BRAFi) monotherapy using vemurafenib (VMF) and dabrafenib and combination therapy using dabrafenib and the MEKi trametinib, have been developed and have led to great advances in malignant melanoma therapy." (PMID 39070550, 2024).